USP11 (ubiquitin specific peptidase 11)
Diseases named in the same sentence as USP11 in open-access papers (continued):
Sharing a sentence is not in itself a finding about the gene and the disease.
colorectal cancer (9 papers, 2021 to 2025). A primary or metastatic malignant neoplasm that affects the colon or rectum. "This study unveiled that Nrf2 received post-transcriptional regulation from a proteasome-associated deubiquitinating enzyme, USP11, in colorectal cancer (CRC)." (PMID 39617751, 2024). "Furthermore, USP11 is functionally implicated in the resistance to 5-fluorouracil in colorectal cancer through activating autophagy by stabilizing valosin-containing protein (VCP)." (PMID 41419456, 2025). "Our previous experiments have confirmed that USP11 can promote autophagy in colorectal cancer cells, however, the underlying mechanisms were still unknown." (PMID 33758608, 2021). "Collectively, these findings highlight the pivotal role of USP11 in promoting EGFR-driven colorectal cancer progression." (PMID 41419456, 2025). "Our study identifies USP11 as a key regulator of colorectal cancer (CRC) progression, acting through two primary signaling pathways: the EGFR and TLR pathways." (PMID 41419456, 2025). "Our team initiated the investigation by assessing USP11 expression levels in colorectal cancer (CRC) tissues by qPCR and IHC, and found that USP11 was significantly upregulated in cancer tissues." (PMID 39617751, 2024). "It has been demonstrated that USP11 promotes colorectal cancer and HCC growth and metastasis by stabilizing NF90 and activating the ERK/MAPK signalling pathway." (PMID 38229475, 2024). "In patients with colorectal cancer and melanoma, the overexpression of USP11 prevents cIAP2 from being degraded, which is related to the low survival rate of patients." (PMID 35359344, 2022). "Taken together, these results suggest that USP11 is involved in the occurrence and development of colorectal cancer." (PMID 35359344, 2022). "Another study also found that circ_DOCK1 inhibits the progression of colorectal cancer by targeting miR-132-3p to interfere with the expression of USP11." (PMID 35359344, 2022). "Circ_DOCK1 interference suppressed cell growth and metastasis, and increased apoptosis of colorectal cancer via decreasing USP11 by increasing miR-132-3p." (PMID 33685455, 2021). "More importantly, the emerging evidence suggests that USP11 can promote the development of colorectal cancer by protecting protein phosphatase 1 via deubiquitination to activate mitogen-activated protein kinase pathway." (PMID 33685455, 2021). "Our study evaluated the oncogenic function of circ_DOCK1 on colorectal cancer development, and we firstly confirmed the circ_DOCK1/miR-132-3p/USP11 axis." (PMID 33685455, 2021). "Finally, the USP11/PPP1CA complex promotes the progression of colorectal cancer by activating the ERK/MAPK signaling pathway." (PMID 35359344, 2022). "Studies have found that USP11 is overexpressed in colorectal cancer tissues." (PMID 35359344, 2022). "The overexpression of USP11 is related to the poor prognosis of colorectal cancer." (PMID 35359344, 2022). "Whether in vivo or in vitro experiments, overexpression of USP11 can promote the growth and metastasis of colorectal cancer cells." (PMID 35359344, 2022). "In this study, we found that the autophagy of colorectal cancer cells with overexpression of USP11 was significantly enhanced after treated with 5-Fu, while the autophagy of colorectal cancer cells with knockdown of USP11 was significantly weakened after treated with 5-Fu." (PMID 33758608, 2021). "This indicates that USP11 could play important roles in the resistance to 5-Fu of colorectal cancer cells." (PMID 33758608, 2021). "In this research, the purposes were to investigate the function of circ_DOCK1 (hsa_circ_0020397) on cell growth, metastasis, and apoptosis in colorectal cancer, and to explore whether it required the circ_DOCK1/miR-132-3p/USP11 network." (PMID 33685455, 2021). "Taken together these data, we hypothesized that USP11 might mediate resistance to 5-Fu by inducing autophagy in colorectal cancer cells and verified the hypothesis in follow-up experiments." (PMID 33758608, 2021).
colorectal cancer (continued). "We have shown that USP11 could promote colorectal cancer, then we wondered whether USP11 is involved in chemotherapy resistance in CRC patients." (PMID 33758608, 2021). "In conclusion, our study displayed that circ_DOCK1 was upregulated in colorectal cancer, and circ_DOCK1 knockdown repressed growth and metastasis, and promoted apoptosis of colorectal cancer cells, possibly via increasing miR-132-3p and decreasing USP11." (PMID 33685455, 2021). "In the present study, we demonstrated that USP11 could induce resistance to 5-Fu in colorectal cancer both in vitro and in vivo via activation of autophagy through stabilizing VCP." (PMID 33758608, 2021). "In this way, the circ_DOCK1/miR-132-3p/USP11 axis participated in colorectal cancer development." (PMID 33685455, 2021). "In conclusion, these findings confirm that USP11 could promote colorectal cancer cells resistance to 5-Fu through inducing autophagy dependent on VCP." (PMID 33758608, 2021). "Furthermore, USP11 expression was markedly enhanced in colorectal cancer tissues." (PMID 33685455, 2021). "However, it's still unknown whether USP11 is relevant with autophagy and affects the efficacy of chemotherapy in colorectal cancer." (PMID 33758608, 2021). "Hence, we hypothesized the circ_DOCK1/miR-132-3p/USP11 axis might be an important network for circ_DOCK1 in colorectal cancer." (PMID 33685455, 2021). "More importantly, USP11 could promote cell growth and metastasis in colorectal cancer." (PMID 33685455, 2021). "Thus, we hypothesized that USP11 could promote resistance to 5-Fu in colorectal cancer by inducing autophagy." (PMID 33758608, 2021). "Interestingly, the findings of another study indicated that USP11 promotes growth and metastasis by stabilizing PPP1CA in colorectal cancer, suggesting that DUBs could have opposite functions via regulating different proteins in diverse diseases." (PMID 37151889, 2023). "However, the current work did not explore the downstream and specific function of USP11 in colorectal cancer, which would be explored in future." (PMID 33685455, 2021).
lung carcinoma (8 papers, 2016 to 2025). "USP11 regulates cell cycle progression and DNA damage response in lung cancer cells in a p21-dependent manner." (PMID 38722330, 2024). "In contrast, USP11 depletion increases sensitivity to ferroptosis induction, which contributes to suppression of lung cancer cell proliferation." (PMID 34742351, 2021). "Studies have shown that the DUB USP11 can bind and promote the deubiquitination modification of NRF2, thereby conferring resistance to ferroptosis in lung cancer cells." (PMID 40136417, 2025). "Consistent with our findings, USP11 has recently been shown to inhibit ferroptosis by stabilizing NRF2 protein levels and promoting the proliferation of lung carcinoma cells under oxidative stress." (PMID 37414755, 2023). "The expression of NFE2L2 is also regulated by ubiquitin specific peptidase 11 (USP11) and activating transcription factor 2 (ATF2) in lung cancer cells." (PMID 34742351, 2021).
colon carcinoma (7 papers, 2017 to 2025). "USP11 acts as a tumor suppressor in lung adenocarcinoma and brain tumors, but has tumor promoting characteristics in colon cancer, melanoma, pancreatic cancer, and cervical cancer." (PMID 29228550, 2017). "In colon cancer, USP11 could bind IGF2BP3 and block its ubiquitination degradation, which then promotes tumor proliferation and metastasis." (PMID 38565547, 2024). "USP11 is a member of the USP family protein that is involved in several cancers including cervical (Lin, Chang & Yu, 2008), lung, liver, brain and colon cancer." (PMID 32655987, 2020). "A previous research demonstrated that elevated USP11 in colorectal cancer cells could protect PPP1CA from proteasome-mediated degradation, thus activating the MAPK pathway and promoting colon cancer cell growth and metastasis." (PMID 35145062, 2022). "We first observed that protein and mRNA levels of USP11, but not any other known PTEN DUBs (such as HAUSP, USP13, and OTUD3), were markedly lower in isogenic PTEN-null (PTEN-/-) HCT116 colon carcinoma cells compared to WT parent (PTEN+/+) or heterozygous (PTEN+/-) cells." (PMID 30733438, 2019).
ovarian carcinoma (7 papers, 2021 to 2025). A malignant neoplasm originating from the surface ovarian epithelium. "Upregulated USP11 expression was found in ovarian cancer and related to poorer prognosis, USP11 promoted epithelial-to-mesenchymal transition by deubiquitinating snails, which finally facilitated the invasion and metastasis of ovarian cancer." (PMID 35715413, 2022). "Further, it has been observed that high expression of USP11 could deubiquitinate and stabilize Snail, thereby promoting the Epithelial-Mesenchymal Transition of ovarian cancer." (PMID 39617751, 2024). "All above researches show that USP11 is a typical oncogenic factor that might be a potential therapeutic target for ovarian cancer patients." (PMID 35715413, 2022). "Targeting USP11-BIP axis might be a therapeutic strategy to improve the chemosensitivity of patients with ovarian cancer." (PMID 35715413, 2022). "Recently, an increasing number of researchers have found that USP11 is involved in the occurrence and development of multiple cancers, such as colorectal, breast, hepatocellular, and ovarian cancers, implying that USP11 is a potential therapeutic target for a variety of cancers." (PMID 35715413, 2022). "Therefore, USP11 is also a potential therapeutic target in ovarian cancer." (PMID 35359344, 2022). "China recently did a lot of work in the discovery of multiple drug resistance mechanisms, including overexpression of the USP11-BIP axis leading to drug resistance, significantly upregulated TTK expression in high-grade serous ovarian carcinoma (HGSOC), and cisplatin-resistant ovarian cancer cells." (PMID 37324006, 2023). "Targeting USP11 might increase the survival and chemosensitivity of ovarian cancer, and USP11 specific/non-specific inhibitors will surely be applied to clinical treatment soon." (PMID 35715413, 2022).
prostate carcinoma (6 papers, 2019 to 2025). A carcinoma that arises from epithelial cells of the prostate gland. "To further analyze the effects of loss of Usp11 on prostate carcinoma in TRAMP mice, we followed cohorts of TRAMP;Usp11+/Y and TRAMP;Usp11-/Y mice by magnetic resonance imaging (MRI) analysis." (PMID 30733438, 2019). "We further investigated the consequences of loss of Usp11 in a mouse model of prostate cancer." (PMID 30733438, 2019). "For example, USP11 promotes tumorigenesis in prostate cancer by deubiquitinating androgen receptor and c-Myc, as well as removing repressive histone marks (H2A-K119Ub) from their gene promoters." (PMID 41207628, 2025). "The downregulation of USP11 in breast, kidney, thyroid and prostate cancers is closely related to PTEN protein instability, regulating the occurrence and progression of these cancers, and is correlated with worsened prognosis." (PMID 36385557, 2022). "PTEN activates the transcription of USP11 by the PI3K/FOXO pathway to enhance its own stability in prostate cancer cell line." (PMID 31592114, 2019). "To determine the clinical relevance of PTEN regulation by USP11, we studied tumor tissue microarrays (TMAs) of human prostate cancer and triple-negative breast cancer (TNBC) samples." (PMID 30733438, 2019). "In addition, USP11 not only regulates the status of prostate cancer via stabilizing PTEN, but also acts as a carrier of cell density to control the physiological dose of PTEN protein." (PMID 35715413, 2022). "We then examined whether USP11 expression levels correlated with PTEN protein levels in the TMAs of 99 prostate cancer and 86 TNBC cases presenting two copies of the PTEN gene." (PMID 30733438, 2019). "A recent article reported that USP11 can deubiquitinate and stabilize the MYC and AR proteins, thereby promoting prostate cancer progression." (PMID 39990228, 2025). "Depletion of USP11 enhanced growth, invasion, and glucose and glutamine metabolism in ERG-negative 22Rv1 human prostate cancer cells stably overexpressing ERG (22Rv1ERG)." (PMID 30733438, 2019). "The ectopic expression of USP11 in PTEN-proficient human prostate cancer cell line DU145 depleted of USP13 or OTUD3 still upregulated PTEN, suggesting that USP11 could be a more potent regulator of PTEN than other DUBs in our assays." (PMID 30733438, 2019).
diffuse large B-cell lymphoma (5 papers, 2018 to 2025). "A comparable trend was observed in the DLBC (diffuse large B-cell lymphoma) dataset, where Usp11 and JAG2 displayed a correlation." (PMID 39904982, 2025). "USP11 stabilizes and enhances Eukayotic translation initiation factor 4B (eIF4B) activity and promotes oncogenic translation in diffuse large B cell lymphoma (DLBCL)." (PMID 36490346, 2022). "Here, in diffuse large B-cell lymphoma, the authors show that fatty acid synthase increases USP11 interaction with and stability of eIF4B via PI3K-S6Kinase signaling, promoting oncogenic protein translation." (PMID 29483509, 2018).
glioma (5 papers, 2015 to 2023). A benign or malignant brain and spinal cord tumor that arises from glial cells (astrocytes, oligodendrocytes, ependymal cells). "USP11 not only restrains the proliferation and invasion of glioblastoma multiforme but also further deterioration of glioma-initiating cells." (PMID 35715413, 2022). "For example, USP11 regulates the stability of promyelocytic leukemia (PML) protein to inhibit the various malignant features of Notch-induced aggressive gliomas." (PMID 35359344, 2022). "The significance of USP11 in glioma tumorigenesis has been demonstrated by its positive regulation on PML, which is downregulated in majority of cancers and played inhibiting cancer role." (PMID 35715413, 2022). "In contrast to its paralogs, USP11 exerts a protective effect in glioma as it stabilizes many tumor suppressors." (PMID 26503449, 2015). "Increasing USP11 or targeting Notch signaling pathway might be a feasible therapeutic strategy for numerous glioma patients." (PMID 35715413, 2022). "Evidence has indicated that USP11 has anti‐tumour activity in lung adenocarcinoma and glioma." (PMID 31993801, 2020).
melanoma (5 papers, 2011 to 2022). A malignant, usually aggressive tumor composed of atypical, neoplastic melanocytes. "USP11 is frequently overexpressed in melanoma and is linked to the proliferation of melanoma cells." (PMID 33369124, 2021). "In melanoma, overexpression of USP11 has been frequently observed and is correlated with poor prognosis." (PMID 33369124, 2021). "Although previous research has shown that USP11 overexpression is frequently found in melanoma and is correlated with a poor prognosis, the potential molecular mechanism of USP11 in melanoma remains indefinitive." (PMID 33369124, 2021). "In congruence with this, our results indicate that USP11 acts as an oncogene, because USP11 overexpression promotes the proliferation of melanoma cells, whereas knockdown of USP11 exhibits the opposite function." (PMID 33369124, 2021). "In the initial screening of melanoma samples, five genes (USP10, USP11, USP22, USP48 and COPS5) were significantly overexpressed, compared with benign nevi." (PMID 21283576, 2011). "We also demonstrated that USP11 promoted the melanoma cells proliferation and tumorigenesis via NONO." (PMID 33369124, 2021). "Similar results were yielded from a CCK‐8 assay, indicating that USP11 mediated the proliferation of melanoma cells through NONO." (PMID 33369124, 2021). "In melanoma tissues, high expression of USP11 and NONO was observed in 15 (46.88%) and 16 cases (50%) respectively, whereas only 8 (25%) and 4 (12.5%) cases respectively in normal skin tissues." (PMID 33369124, 2021). "This implies that targeting USP11/NONO might be a therapeutic strategy for melanoma, providing a new direction for clinical treatment options." (PMID 35715413, 2022). "Thus, our study shows that USP11‐NONO signalling axis plays a critical role in melanoma proliferation." (PMID 33369124, 2021). "Moreover, a significant positive correlation between USP11 and NONO concentrations was found in clinical melanoma samples, implying that USP11 is a potential target candidate in the diagnosis and treatment of melanoma." (PMID 33369124, 2021). "Functionally, USP11 mediated melanoma cell proliferation via the regulation of NONO levels because ablation of USP11 inhibits the proliferation which could be rescued by ectopic expression of NONO protein." (PMID 33369124, 2021). "Furthermore, we demonstrate that USP11 mediates the proliferation of melanoma cells via NONO because the effect of USP11 knockdown on melanoma cells could be rescued by introducing NONO." (PMID 33369124, 2021). "Here, we report that USP11 and NONO colocalize and interact with each other in the nucleus of melanoma cells." (PMID 33369124, 2021). "Collectively, these results demonstrate that USP11 is a new deubiquitinase of NONO and that the signalling axis of USP11‐NONO is significantly involved in melanoma proliferation." (PMID 33369124, 2021). "Moreover, a significant positive correlation between USP11 and NONO abundances were found in clinical melanoma samples." (PMID 33369124, 2021). "Furthermore, we investigated the interaction of endogenous USP11 and NONO in melanoma cells SK‐Mel‐28 and A375 using co‐IP." (PMID 33369124, 2021). "Moreover, there was a significant positive correlation (R = 0.4384, P = 0.0121) between USP11 and NONO in those melanoma tissues." (PMID 33369124, 2021). "Moreover, a significant positive correlation between USP11 and NONO concentrations was found in clinical melanoma samples." (PMID 33369124, 2021). "This suggests that both USP11 and NONO are overexpressed in melanoma." (PMID 33369124, 2021). "However, future studies are needed to ascertain how USP11 expression is regulated and how transcription and post‐translational modification of NONO coordinate the cellular level of NONO, which will provide clues for effective control of melanoma." (PMID 33369124, 2021).
squamous cell carcinoma (5 papers, 2017 to 2022). A carcinoma arising from squamous epithelial cells. "For example, USP11 can prevent the progression of squamous cell carcinoma by stabilizing ARID1A." (PMID 35359344, 2022). "As for the role of USP11 in the remaining squamous cell carcinoma, more researches are needed." (PMID 35715413, 2022). "Targeting Trim32/USP11/ARID1A/SDC2 might be a potential therapeutic strategy for patients with squamous cell carcinoma." (PMID 35715413, 2022). "To determine the role of USP11 in human skin cancer, we evaluated the protein levels of USP11 by immunohistochemical staining in normal human skin tissue (Normal, n = 21), actinic keratosis (AK, pre-malignant, n = 15), and squamous cell carcinoma (SCC, malignant, n = 16)." (PMID 29228550, 2017). "Research has found that TRIM32 depletion can inhibit the proliferation, metastasis, and chemotherapy resistance of squamous cell carcinoma (SCC) by stabilizing ARID1A, while USP11 depletion can promote the development of SCC by promoting the degradation of ARID1A." (PMID 35359344, 2022).
brain tumors (4 papers, 2017 to 2024). "USP11 was reported to have tumour‐suppressive functions in brain tumours and serve as a negative regulator of the cell cycle." (PMID 31993801, 2020). "Another study showed that USP11 deubiquitinates and stabilizes promyelocytic leukaemia protein, thereby counteracting the functions of ubiquitin ligases and controlling Notch‐induced malignancy in brain tumours." (PMID 38229475, 2024).